CD4 (CD4 molecule)
Diseases named in the same sentence as CD4 in open-access papers (continued):
Sharing a sentence is not in itself a finding about the gene and the disease.
appendicitis (7 papers, 2012 to 2025). Acute inflammation of the vermiform appendix. "These analyses showed a disruption of local T cell responses, and increased frequencies of effector IL-17A-producing CD4+ T cells in the appendix of children with complex compared to simple appendicitis." (PMID 38239362, 2023). "In line with the increased differentiated phenotype, cytokine production of in particular IL-17A by CD4+ T cells was increased in children with complex compared to simple appendicitis." (PMID 38239362, 2023). "Increased frequencies of IL-17A+ CD4+ T cells were observed in the epithelium of the appendix of children with complex appendicitis compared to simple appendicitis." (PMID 38239362, 2023). "IL-17A production of epithelial CD4+ T cells derived from the appendix of children with complex compared to simple appendicitis was increased upon P/I-stimulation." (PMID 38239362, 2023). "T cells in complex appendicitis displayed an increased differentiated phenotype compared to simple appendicitis, including a loss of both CD27 and CD28 by CD4+ T cells and to a lesser extent by CD8+ T cells." (PMID 38239362, 2023). "negatively correlated with IL-17A+ CD4+ T cells in children with appendicitis." (PMID 38239362, 2023). "Furthermore, frequencies of IL-17A+ CD4+ T cells correlated with a dysregulation of the appendiceal microbiota in children with complex appendicitis." (PMID 38239362, 2023). "Appendiceal CD4+ T cell populations in children with complex appendicitis were characterized by a decrease of molecules mediating tissue-residency and an increase of IL-17A production compared to children with simple appendicitis." (PMID 38239362, 2023). "In all tissue layers of the appendix combined, a trend towards decreased frequencies of naïve CD4+ T cells (Tn; CCR7+CD45RA+) was observed in children with complex compared to simple appendicitis." (PMID 38239362, 2023). "Frequencies of phenotypic tissue-resident memory CD69+CD4+ T cells and CD69+CD8+ T cells were decreased in children with complex compared to simple appendicitis, indicating disruption of local tissue-resident immune responses." (PMID 38239362, 2023). "In line, a trend towards increased frequencies of effecter memory CD4+ T cells (Tem; CCR7-CD45RA-) was observed in all layers of the appendix combined in children with complex compared to simple appendicitis." (PMID 38239362, 2023). "In our series, in the appendiceal mucosa, macrophages cell rate (CD163+), T helper lymphocytes (CD4+), T cytotoxic lymphocytes (CD8+) and activated cytotoxic lymphocytes (CD8+CD69+) were all significantly lower in UC patients compared to appendicitis and CC patients." (PMID 40827526, 2025). "The immunohistochemical analysis showed a greater number of CD20 B-lymphocytes, memory cells CD45R0, Ki-67+ cells, CD3, CD4, CD8, and CD45 T lymphocytes in the suppurative appendicitis compared to the control group, which differs from the results of this study." (PMID 41470162, 2025). "This augmented pro-inflammatory activity of CD4+ T cells in complex appendicitis is in line with the reduced expression of CD27 and CD28 indicating an increased effector phenotype of CD4+ T cells in the appendix of children with complex compared to simple appendicitis." (PMID 38239362, 2023). "Previous studies suggest that CD4+ T cells and CD8+ T cells are affected in the appendix during inflammation and may differ in frequencies between children with simple and complex appendicitis." (PMID 38239362, 2023). "The subgroup analysis of HIV-positive patients indicated that a CD4 < 200 cells/mm3 and ART naivety or non-compliance were risk factors for mortality in patients with acute appendicitis." (PMID 37580602, 2023). "In our study, high-grade appendicitis (AAST 4 or 5) was associated with increased mortality, although this was not shown to be influenced by HIV status or CD4 count." (PMID 37580602, 2023).
appendicitis (continued). "However, in patients with typically surgical problems, e.g., appendicitis and gastrointestinal perforation, early surgery allows for rapid recovery similar to normal surgical patients irrespective of CD4 count." (PMID 22583551, 2012).
bacterial meningitis (7 papers, 2010 to 2024). Inflammation of the membranes surrounding the brain and spinal cord due to a bacterial infection. "Regarding absolute numbers of CSF immune cell subtypes, B cells, CD4, and CD8 T cells were significantly elevated in LNB, Lues, bacterial meningitis, viral meningitis, and CIS-RRMS when compared to our control group with NIND." (PMID 31727097, 2019). "In contrast, the CD4 T cell fraction was significantly reduced in LNB and bacterial meningitis most likely due to a relative percentage increase of other populations." (PMID 31727097, 2019).
benign prostatic hyperplasia (7 papers, 2013 to 2025). A non-cancerous nodular enlargement of the prostate gland. "The etiopathogenesis of benign prostate hyperplasia is believed to be the infiltration of activated CD4+ T lymphocytes and the release of inflammatory cytokines." (PMID 36051392, 2022). "Moreover, Propionibacterium acnes infection of the prostate organ may have a major impact on the infiltration of CD4+, IL-17+, and Treg cells into prostate tissue in patients with benign prostatic hyperplasia (BPH)." (PMID 38745115, 2024). "The expression of T-cell immunoglobulin domain and mucin domain-containing molecule 3 (TIM-3) encoded by HAVCR2 in CD4+ and CD8+ T cells of the PCa patients was significantly increased compared with benign prostatic hyperplasia, suggesting that it may affect the development and progression of PCa." (PMID 35463369, 2022).
bronchitis (7 papers, 2010 to 2025). An acute or chronic inflammatory process affecting the bronchi. "Intranasal infection of mice or intra-bronchial infection of non-human primates with MAC leads to activation of both CD4 and CD8 T cells." (PMID 30837992, 2019).
carotid atherosclerosis (7 papers, 2018 to 2025). A thickening and loss of elasticity of the walls of carotid arteries that occur with formation of atherosclerotic plaques. "In addition, specific T cells subsets such CD4+ CCR5 + T cells were independently associated with development of carotid atherosclerosis in SLE patient in this study." (PMID 33743717, 2021). "A subgroup comparison showed that patients with progression of carotid atherosclerosis had higher relative numbers of T-regulatory (CD4+CD4+CD25+CD127−) cells (6.55% (5.25–8.30) versus 5.80% (5.20–6.10), p = 0.0278)." (PMID 37569579, 2023).
cerebrovascular disease (7 papers, 2019 to 2024). "After a univariate regression analysis, we observed that cerebrovascular disease, thrombin time, CD4 count, erythrocyte sedimentation rate and HA were associated with the risk of death (p < 0.05)." (PMID 38881657, 2024). "Additionally, the review covers the roles of ICPs in modulating CD4+Foxp3+ regulatory T cells (Tregs), T cells, and innate immune cells in various CVDs and cerebrovascular diseases." (PMID 39926714, 2024).
chronic pancreatitis (7 papers, 2020 to 2025). A chronic inflammatory process causing damage and fibrosis of the pancreatic parenchyma. "In CD4+ T lymphocytes from chronic pancreatitis tissues, the knockdown of the transcription factor Bach2 downregulates OTUD5 expression." (PMID 37190070, 2023). "The exposure of BTB and CNC homologous 2(Bach2)-silenced CD4+ T lymphocytes to chronic pancreatitis tissue extracts leads to a decrease in OTUD5 and increased Th17 cell differentiation." (PMID 37190070, 2023). "There was increased infiltration of B, CD4+, CD8+, Treg and γδT cells in KC;iASPPΔ8/Δ8 pancreata following chronic pancreatitis relative to KC." (PMID 37270580, 2023). "The presence of CD4+ and CD8+ T-lymphocytes and perforin-expressing cells in the fibrotic tissue in chronic pancreatitis modulate the severity of the disease." (PMID 32796685, 2020). "Using immunohistochemical assays, another study discovered that although CD3+ T cells and SMA+ fibroblasts were evenly spread in chronic pancreatitis (CP) and PDAC, CD4+ and CD8+ T cells were notably lower in number, while CD25+(CD4+) as well as FoxP3+(CD4+) regulatory T cells were elevated in PDAC." (PMID 40699746, 2025). "Indeed, KC;iASPPΔ8/Δ8 pancreas-infiltrating CD4+ and CD8+ T cells secreted substantially less (p = 0.037) TNF-α and IFN-γ following chronic pancreatitis." (PMID 36746936, 2023).
crescentic glomerulonephritis (7 papers, 2021 to 2025). A histopathologic term for a pattern of diseases characterized by extensive crescent formation in the glomeruli; patients present clinically with rapid deterioration of renal function, and possible progression to end-stage renal failure within weeks or months. "Moreover, in experimental anti-MPO-associated crescentic glomerulonephritis, mice depleted of CD4+ T cells and CD8+ T cells developed significantly improved renal prognosis." (PMID 34289887, 2021). "Using an experimental model of crescentic glomerulonephritis, we show that the steroid-induced decrease in renal CD4+ T cells is a consequence of reduced T cell recruitment, which is associated with an ameliorated disease course." (PMID 36355429, 2023). "GC has been shown to inhibit the induction of CXCL10 in tubular epithelial cells to prevent renal infiltration of CXCR3+CD4+ T cells and subsequent renal tissue damage in patents and mice with crescentic glomerulonephritis." (PMID 39619227, 2023).
cystitis (7 papers, 2008 to 2026). Inflammation of the urinary bladder. "UTI89HC mice were susceptible to developing recurrent UTI89 cystitis, whether they were initially treated with anti-CD4/8 or isotype." (PMID 30543708, 2018). "Considered together, these findings show CYP-induced cystitis is associated with considerable reduction in the percentage of T helper lymphocytes in the spleen and iliac lymph nodes, but an increase in both the percentage and the number of CD4+ T cells in the urinary bladder." (PMID 18957084, 2008). "In HSCT recipients treated for BKV-related cystitis, absolute CD4+ T-cell numbers and renal function correlated with BKV-specific cellular responses (p = 0.03 and 0.01, respectively)." (PMID 37112757, 2023). "We found that depletion of CD4+ and CD8+ T cell subsets impaired the ability of the host to clear CFT073 infections and rendered mice with a history of CFT073 cystitis lasting four weeks susceptible to recurrent CFT073 cystitis upon challenge." (PMID 30543708, 2018). "Overall, this study suggests that CXCL10 is a mediator of CD4+ T cell, mast cell, and neutrophil infiltration to the urinary bladder (effector) during cystitis." (PMID 24278169, 2013). "There is a single previous description of murine bladder ILC3s, which identified CD4+ ILC3s, but here we show that NKp46+ ILC3s are also present and we directly profiled their cytokine production and function in the context of bladder infection." (PMID 35845169, 2022). "However, four of 11 mice that received anti-CD4/8 during their initial chronic infection developed recurrent chronic CFT073 cystitis lasting four weeks and one mouse was a “late resolver,” similar to what is seen during CFT073 infection of juvenile naive mice." (PMID 30543708, 2018). "We found that the combined depletion of CD4+ and CD8+ T cell subsets during the initial CFT073 infection increased the incidence of chronic cystitis and rendered mice susceptible to recurrent chronic CFT073 cystitis." (PMID 30543708, 2018). "Depletion of both CD4+ and CD8+ T cell subsets during the initial infection was necessary to prevent “late resolution” of chronic CFT073 cystitis and render the host susceptible to recurrent chronic CFT073 cystitis, suggesting that one subset may compensate for the loss of the other." (PMID 30543708, 2018). "After the induction of cystitis with CYP, the percentage of CD4+ T cells decreased from 21.6% to 2.4% of the total leukocyte population in the spleen." (PMID 18957084, 2008). "Prior work shows that mice subjected to cyclophosphamide-induced cystitis alongside an IP-10 inhibitor exhibited a decreased number of CD4+ T-cells compared to mice that did not receive an IP-10 inhibitor." (PMID 40809119, 2024). "In the combined CD4+ and CD8+ T cell depleted group, the rate of chronic CFT073 cystitis was 61%, vs. 40% in the isotype-treated group, and CFT073 urine titers at 28 dpi were significantly elevated in the combined T cell-depleted mice relative to isotype-treated controls." (PMID 30543708, 2018). "Depletion of CD4+ and CD8+ T cell subsets did not affect the incidence of chronic cystitis caused by UTI89." (PMID 30543708, 2018). "We also show that the number of CD4+ T cells, mast cells, natural killer (NK) cells, and NKT cells were increased at systemic (spleen) and mucosal (urinary bladder and iliac lymph nodes) sites, following CYP-induced cystitis in mice." (PMID 18957084, 2008). "Our results show that CXCL10 blockade does not affect the percentage of CD4+ T cells in the spleen of naïve mice, but inhibition of CXCL10 in CYP-treated mice with cystitis lead to an increase in the percentage of T helper splenocytes." (PMID 18957084, 2008).
disseminated candidiasis (7 papers, 2014 to 2025). Systemic candidiasis occurs when Candida yeast enters the bloodstream and may spread (becoming disseminated candidiasis) to other organs, including the central nervous system, kidneys, liver, bones, muscles, joints, spleen, or eyes. "The kidney serves as the primary target in disseminated candidiasis, yet exhibits impaired recruitment of antigen-specific CD4+ T cells." (PMID 40953078, 2025). "Liquiritigenin, a flavonoid, increased the survival time of mice infected with C. albicans, this licorice root component protecting the mice against disseminated candidiasis by a CD4+ Th1 immune response." (PMID 35262409, 2022). "Although absolute numbers were not determined, the increased relative abundance of Th2 and Th9 CD4+ cells in spleens of infected Nos3-/- mice suggest that these T helper subsets enhance protective immunity, and their role in human disseminated candidiasis merits further investigation." (PMID 31671151, 2019). "Similarly to the case with other studies of disseminated candidiasis, the percentages of CD4+ T cells were higher than those of CD8+ T cells at all time points tested." (PMID 27799331, 2017). "The susceptibility of Treg-and Th17-cell deficient patients with autoimmune polyendocrine syndromes to chronic mucocutaneous candidiasis, but not disseminated candidiasis 24, also supports the view that different CD4+ T-cell responses protect against C. albicans infection at different locations." (PMID 24435677, 2014).
Failure to thrive (7 papers, 2010 to 2023). Failure to thrive (FTT) refers to a child whose physical growth is substantially below the norm. "We previously reported the results of a study looking at the association between CD4+ T lymphocyte percentage and functional T lymphocyte immune response as assessed in the lymphocyte proliferation assay in HIV+ children with failure to thrive." (PMID 22292110, 2011). "Patients have generally severe CD4 T-cell lymphopenia, and hypogammaglobulinemia and lack Ag-specific responses resulting in chronic diarrhea, recurrent viral, parasitic and bacterial infections, and failure to thrive." (PMID 24062773, 2013).
gallbladder cancer (7 papers, 2003 to 2025). "Taking the evidence derived from the patients with gall bladder cancer into account, we speculate that immunonutrition may be associated with a more favorable outcome compared to standard nutrition owing to its impact on CD4+/CD8+ ratio." (PMID 36326418, 2022). "Immunofluorescence staining of gallbladder carcinoma tissue reveals that CD4 cells highly express the Treg cell marker, while CD8 cells show high expression of the inhibitory molecule PD-1 and the cytotoxic molecule GZMB." (PMID 41487509, 2025). "We examined 45 cases of gallbladder cancer and 65 cases of benign gallbladder diseases for CD4+ T cells, CD8+ T cells, natural killer cells (NKCs), and dendritic cells (DCs)." (PMID 14583778, 2003). "Their finding shows that the existence of CD4+ T cells is not adequate to propose a tumor in a milieu containing decreased CD8+ T cells and that Foxp3+ T cells might have a negative effect on the potential of CD8+ T cells for fighting against gallbladder cancer." (PMID 36326418, 2022).
genital herpes (7 papers, 2006 to 2025). Herpes simplex infection of the genitals, most commonly caused by the herpes simplex-2 virus. "Pulling more antiviral tissue-resident effector CD4+ and CD8+ TRM cells within latently infected DRG and VMC of guinea pigs is associated with protection from recurrent genital herpes." (PMID 41012114, 2025). "In conclusion, the human FRT is richly and persistently infiltrated with HSV-2-specific CD8 and CD4 T cells in immunocompetent persons with a clinical history of recurrent genital herpes." (PMID 35432373, 2022). "Conversely, depletion of functional CD4+ and CD8+ T cells in the latently infected and vaccinated guinea pigs and mice was associated with increased virus shedding, severity, and longevity of genital herpes." (PMID 41012114, 2025). "Indeed, increased CD4+ mediated production of IFNγ has previously been reported as a consequence of using liposome-DNA complexes as an adjuvant for genital herpes vaccines and for delivery of a mycobacterial hsp65 DNA vaccine." (PMID 20637091, 2010). "It is noteworthy that the CD4 response could be correlated to the severity of genital herpes." (PMID 16822314, 2006). "It is recommended that intermittent cessation of suppressive antiviral therapy for genital herpes should occur, especially in those in whom there is also sustained HIV viral suppression and rising CD4 cell counts." (PMID 39374063, 2025). "The patient is a 52-year-old African American man with a past medical history of HIV infection (on antiretroviral therapy, CD4 count 399 cells/μL, and undetectable HIV viral load) and recurrent genital herpes." (PMID 28373917, 2017). "An IFN-γ ELISPOT assay has been used to measure CD4 and CD8 T-cell responses in subjects with genital herpes." (PMID 16822314, 2006). "Using overlapping synthetic peptide libraries, an IFN-γ ELISPOT assay was established that could measure CD4 and CD8 T-cell responses to HSV-2 antigens in patients with genital herpes." (PMID 16822314, 2006).
goiter (7 papers, 2017 to 2024). Enlargement of the thyroid gland usually caused by lack of iodine in the diet, hyperthyroidism, or thyroid nodules. "Among the parameters of the lymphocyte population, the elevated CD4+/CD8+ ratio appears to be positively correlated with higher fT3 levels and goiter size at diagnosis, higher TRAb titre in the first 2 years, and higher ATD dose in the first year after the diagnosis." (PMID 35654927, 2022).
Graves' orbitopathy (7 papers, 2017 to 2024). "CD4+ cytotoxic T lymphocytes (CTLs) were recently implicated in immune-mediated inflammation and fibrosis progression of Graves’ orbitopathy (GO)." (PMID 36580373, 2023). "In a previous study, we discovered that CD4 CTLs had elevated cytotoxic function in patients with Graves orbitopathy (GO), indicating that there might be regulators of the cytotoxicity of CD4 CTLs in GO." (PMID 36737819, 2023). "Meanwhile, the percentage of CD4+ T cells and the ratio of CD4+/CD8+ cells were higher in both GD and Graves’ ophthalmopathy than those of healthy controls." (PMID 29163513, 2017).